IL17F (interleukin 17F)
Diseases named in the same sentence as IL17F in open-access papers (continued):
Sharing a sentence is not in itself a finding about the gene and the disease.
colitis (continued). "The contrasting effects of IL-17F and IL-17A have also been observed in intestinal inflammation: IL-17F deficiency reduced while IL-17A deficiency exacerbated DSS induced colitis." (PMID 22509371, 2012). "In contrast, DSS-induced colitis mice that received TcES exhibited significant decreases in the production of TNF-α, IL-1β, and IL-33, as well as Th17-associated cytokines such as IL-23 and IL-17F." (PMID 40576745, 2025). "Indeed, blockade of both IL-17A and IL-17F ameliorates colitis, while inhibition of only IL-17A is insufficient." (PMID 39379604, 2024). "This dichotomy, despite both IL-17A and IL-17F acting on the same receptor, implies that each may play distinct roles in the initiation and progression of colitis." (PMID 39379604, 2024). "Interestingly, while blocking IL-17A can exacerbate colitis, perturbation of IL-17F has been reported to reduce disease activity in a DSS-induced colitis model." (PMID 39379604, 2024). "In contrast, the alleviation of DSS-induced colitis progression in Nsun2cKO mice could be reversed by injecting recombinant mouse-IL-17A (rIL-17A), IL-17F (rIL-17F), or both." (PMID 36792629, 2023). "We further investigated the function of IL-17A/IL-17F in DSS-induced colitis mouse model." (PMID 36792629, 2023). "Deletion of Bcl6 results in dysregulation of the LTi-like ILC3 transcriptional program and markedly enhances expression of IL-17A and IL-17F in LTi-like ILC3, in a manner in part dependent upon the commensal microbiota - and associated with worsened inflammation in a model of colitis." (PMID 37950867, 2023). "IL-17F has been found to be an effective target for the treatment of colitis because Il-17f–/– mice may resist the development of colitis." (PMID 35392087, 2022). "Altogether, the increased mTOR activity caused by TSC1 deficiency in macrophages might contribute to the accelerated DSS-induced colitis in TSC1cKO mice and high expression of IL-17A, IL-17F, and IFN-γ in macrophages." (PMID 36465179, 2022). "Reduced expression of Il-17f mRNA in colitis mice might compromise the intestinal defense mechanism." (PMID 35889745, 2022). "In contrast, IL‐17F deficiency resulted in reduced colitis caused by DSS, suggesting that IL‐17F may exacerbate the intestinal inflammation." (PMID 33300279, 2021). "IL-17A and IL-17F play critical roles in the intestinal immune response during colitis." (PMID 32391010, 2020). "However, in the experimental colitis mouse model neutralization of both IL‐17A and IL‐17F ameliorated colitis, whereas neutralization of IL‐17A or IL‐17F alone had limited effect." (PMID 31850514, 2020). "Indeed, IL-17A was protective against colitis mainly by ensuring integrity of the gut mucosa, while IL-17F was proinflammatory." (PMID 33244315, 2020). "Whereas IL-17F level was increased, leading to colitis progression in ArgmyeKO mice." (PMID 32391010, 2020). "Because colitis often anticipates colon cancer, a microbiota-modulated, tumor promoting role for IL-17F can be hypothesized, and it needs to be proven in in vivo experimental settings." (PMID 33244315, 2020). "Increased level of IL-17A and reduced level of IL-17F alleviated colitis in mice consequently." (PMID 32391010, 2020). "DSS colitis and TNBS-relapsing colitis are significantly decreased in IL-21-deficient mice, which is associated with reduced expression of Th17 cell-related genes (IL-17, IL-17F, and RORγt) in the colon tissue." (PMID 31886308, 2019). "The gene encoding IL17F, that promotes colitis in mice, was not inhibited upon IL12 stimulation; reinforcing the concept that IL12 induces the generation of pathogenic Th1* cells in inflamed mLNs." (PMID 31191543, 2019). "Genome-wide association scan data indicate a role played by Th17 cells in IBD, and a combined blockade of IL-17A and IL-17F could obviously prevent the development of experimental colitis." (PMID 30563054, 2018).
colitis (continued). "However, in other systems, such as DSS colitis, the function of IL-17F appears to oppose that of IL-17A, exacerbating disease." (PMID 23405904, 2013). "However, IL-17F suppression was effective in a colitis mouse model, indicating that IL-17A and IL-17F could have differential roles in the gut." (PMID 37600764, 2023). "However, IL-17F also promotes the inflammatory pathology of colitis." (PMID 35889745, 2022). "ILC3 are a dominant source of IL-17F after induction of colitis in Rag1−/− mice, upon oral infection with Candida albicans and following skin wounding, suggesting that IL-17F production by ILC3 may play critical roles in inflammation and immunity or resolving immune responses." (PMID 29085366, 2017). "Conversely, and opposed to the tissue-protective effects described for IL-17A and IL-22, it has been reported that IL-17F-deficient mice develop milder DSS-induced colitic symptoms than wild-type animals, thus suggesting that IL-17F exacerbates inflammation in this experimental model of colitis." (PMID 25101191, 2014). "Th17 cytokines, such as IL-17A, IL-17F, IL-21, and IL-22, have a dual effect on IBD, attenuating or increasing effects in the gut, as shown in experimental colitis models." (PMID 40565877, 2025). "The results showed that neutralization of IL-17A, IL-17F, or both substantially alleviated the DSS-induced colitis development in wild-type mice, with more obvious effect when simultaneously blocking both." (PMID 36792629, 2023). "The administration of antibiotics inhibited the IL-17A, IL-17F and IFNγ-expressing cells in the LILP of both WT and Rap1KO mice, and prevented the development of colitis, indicating that colitis is developed in microbiota-dependent manner in Rap1KO mice." (PMID 35246619, 2022). "During colitis, TWD increased expression of Tnf by 2.5-fold, Il1b by 2.8-fold, Il4 by 4.8-fold, Il6 by 3.3-fold, Ifng by 3.8, and Il17f by 4.2-fold as compared to mice fed the AIN diet." (PMID 32093192, 2020). "We have identified distinct roles of IL-17A and IL-17F in modulating DSS-induced colitis in mice and we demonstrated the benefit of quercetin in colitis dependent on Arg-1 secreted by MDSC after ESR/STAT3 activation." (PMID 32391010, 2020). "On one hand, disease promoting effects in mouse models of colitis were ascribed to IL17A/F-mediated signaling as blocking IL17A and IL17F ameliorated disease." (PMID 29416538, 2018). "In contrast, when IL17A and IL17F were neutralized in the presence of IFNγ-producing cells minimal effect on weight loss or histopathological scores was observed indicating that inhibition of Th17 cytokine per se is not sufficient for the protection of colitis induction (data not shown)." (PMID 29416538, 2018). "To further determine which TH17 cytokines are responsible for inhibiting chemokine expression and protect the Tak1ΔM/ΔM mice against colitis and CRC, we performed intracellular staining of key TH17 cytokines (IL-17A, IL-17F, IL-21, and IL-22) in CD4+ cells from intestinal LP." (PMID 40749055, 2025). "On the other hand, neutralization of both IL-17A and IL-17F ameliorated colitis at early administration, but administration of IL-17A or IL-17F did not." (PMID 40565877, 2025). "Though we suspect that altered Th17 cell trafficking and function play a role in reduced disease in WIN 18,446-treated Mdr1a−/− mice, we did not observe changes in serum IL17F or IL17A associated with WIN 18,446 treatment or colitis severity." (PMID 37764666, 2023). "Additionally, the expression of Il-22 (interleukin 22), Il-17f (interleukin 17f), and Rorγt (RAR-related orphan receptor gamma) were reduced in colitis mice." (PMID 35889745, 2022). "Recently, the suppression of IL-17F, but not of IL-17A, was found to protect against colitis by inducing Treg cells." (PMID 34395637, 2021). "Antibody against IL-17F was effective in treating chemically induced colitis, while antibody to IL-17A was not." (PMID 34539646, 2021).
colitis (continued). "Collectively, attenuated colitis requires increased IL-17A in the colorectum, but not IL-17F, to initiate protective factor synthesis." (PMID 32391010, 2020). "IL-17A expressed by TH17 cell increased obviously in PP and mLN, whereas IL-17F levels decreased in the presence of high levels of MDSC-derived Arg-1, proving once again that TH17 cell polarization is facilitated by Arg-1 expressed by MDSC during colitis." (PMID 32391010, 2020). "IL-17F, at difference to IL-17A, is not required in several T-cell-dependent autoimmune diseases in mice, while being pathogenic in DSS colitis model and in acute allergic responses in the lung." (PMID 30127781, 2018). "It is probable that the IL-17 R KO mice would not respond to either IL-17A or IL-17F, suggesting that inhibition of both forms of IL-17 is needed for attenuation of colitis." (PMID 22506136, 2012). "IL-17F (closest in sequence homology to IL-17A), but not IL-17A, can reduce the presence of Treg-inducing Clostridium cluster XIVa in colonic microbiota, and IL-17F drives intestinal pathology in a T-cell transfer mouse model of colitis." (PMID 38567051, 2023). "Although the Th17-cell subset is most prominently associated with IL-23R function, our recent work suggests that the immunopathology driven by Red 40 and IL-23 does not depend on classical Th17 responses, as blocking IL-17A and IL-17F fails to prevent colitis development in R23FR mice." (PMID 35468944, 2022). "Therefore, Ifng−/− CD4 CD45RBhi T cells were transferred into Rag1−/−Ifng−/− mice for colitis induction and recipient mice were treated with either isotype control antibody or neutralizing antibodies against IL17A and against IL17F twice a week for the duration of the experiment." (PMID 29416538, 2018). "In the dextran-sodium-sulfate- (DSS-) induced colitis model, in which disease progression is primarily due to increased neutrophilic infiltration of the inflamed tissue, mice lacking IL-17F or IL-17A or mice treated with an anti-IL-17A antibody show severe weight loss and colonic epithelial damage." (PMID 22229105, 2012). "This hypothesis is supported by studies performed by Leppkes and colleagues showing that transfer of IL-17A-, IL-17F-, or IL-22-deficient T lymphocytes into RAG1-null mice induces severe colitis that is indistinguishable from that caused by wild-type cells." (PMID 22082127, 2011). "IL-17F-/- mice showed a higher resistance to IBD induction as compared with IL-17A knockout mice, and neutralization of IL-17F, not IL-17A, alleviated colitis progression in mice, indicating a pathologic role of IL-17F in autoimmune disease." (PMID 32391010, 2020). "Colitis induction in the absence of IFNγ-producing T cells is preferentially driven by Th17-related mediators including IL17A and IL17F." (PMID 29416538, 2018). "Intriguingly, IL-17F production by TH17 cells was decreased in the mLN, but not in the PP, which is in line with a report that lower IL-17F level alleviates DSS-induced colitis in mice." (PMID 32391010, 2020). "In contrast, when IL17A and IL17F were neutralized in the presence of IFNγ-producing cells, the histopathological assessment revealed severe colitis although the total score was slightly lower in anti-IL17A and IL17F treated mice compared to untreated recipient mice (data not shown)." (PMID 29416538, 2018).
autoimmune disease (54 papers, 2011 to 2026). A disorder resulting from loss of function or tissue destruction of an organ or multiple organs, arising from humoral or cellular immune responses of the individual to their own tissue constituents. "Although IL-17A and IL-17F have protective roles against certain infections, they are also key pathogenic cytokines in T cell-mediated autoimmune disease pathology." (PMID 40127923, 2025). "IL-17F single nucleotide polymorphism (SNP) can affect IL-17F expression and activity and this can lead to the increased susceptibility to several autoimmune diseases." (PMID 38871733, 2024). "Its human orthologs, IL-17A and IL-17F, are implicated in autoimmune disease, chronic asthma, chronic mucocutaneous candidiasis, rhinitis, and MS." (PMID 34281170, 2021). "All these findings support that IL-17F plays a more important pathogenic role in autoimmune disease." (PMID 28210632, 2017). "Th17 cells differentiate in response to IL-1β, IL-6, IL-23, and TNF-α; secrete IL-17A, IL-17F, and IL-21; and play a critical pathogenic role in T cell-mediated autoimmune diseases." (PMID 28458638, 2017). "Th17 cells, a CD4 T helper subset characterized by the production of IL-17A, IL-17F, IL-21, and IL-22 cytokines, are implicated in the pathogenesis of many autoimmune diseases." (PMID 23505568, 2013). "Because IL-17A and IL-17F are critical cytokines produced by Th17 cells and have been linked to numerous autoimmune diseases, we further investigated the role of TCF-1 in Th17 differentiation." (PMID 21935461, 2011). "Both IL-17A and IL-17F can generate homodimers or heterodimers and bind to heterodimeric IL-17RA and IL-17RC complexes, thereby activating downstream signaling transduction for host defense, autoimmune disease, or inflammation associated biological effects." (PMID 36274974, 2022). "However, there are no studies focusing on the clinical relevance and pathogenic roles of IL-17F in pSS and many other autoimmune diseases." (PMID 28210632, 2017). "IL-17A and IL-17F are primarily produced by a subset of T cells called Th17 and are highly homologous, which have been linked to cytokine and chemokine production in various inflammatory and/or autoimmune diseases, such as RA." (PMID 26252209, 2015). "IL-17F, in conjunction with IL-17A, contributes significantly to the onset and progression of various chronic inflammatory and autoimmune diseases." (PMID 40536951, 2026). "The IL-17 family, comprising six structurally similar members (IL-17A to IL-17F), has garnered substantial research attention given the well-characterized proinflammatory role of its prototypical member IL-17A in autoimmune diseases." (PMID 41007866, 2025). "Our previous studies in patients with autoimmune diseases documented the important role of the SNPs located within genes coding for IL-17A, IL-17F cytokines as well as their IL-17RA and IL-17RC receptors." (PMID 38792460, 2024). "Th17 cells, known for their role in the inflammatory cascade of autoimmune diseases and as primary producers of IL-17 (including IL-17A and IL-17F), displayed a significant upregulation of gene sets implicated in IL-17 production." (PMID 39867884, 2024). "Treatment with antibodies that neutralize IL-17A and IL-17F (anti-IL-17A/F) is currently used as a therapy for patients with inflammatory and autoimmune diseases such a psoriasis." (PMID 37291218, 2023). "In the mid-2000s, an important role was attributed to these IL-17A and IL-17F producing lymphocytes in the context of autoimmune diseases." (PMID 35301281, 2022). "Because of the important role of IL-17A and IL-17F in inducing tissue inflammation, Th17 cells have been shown to play a critical role in the etiopathogenesis of many autoimmune diseases, in which Th1 was originally considered as a dominant factor." (PMID 34576041, 2021). "Interleukin 17A (IL-17A) and interleukin 17F (IL-17F) appear to play important role in pathogenesis of some autoimmune diseases." (PMID 32724117, 2020).
autoimmune disease (continued). "Upregulated IL-17A and IL-17F expressions are found during inflammation, And patients with severe allergies, chronic inflammatory diseases, and autoimmune diseases can have high levels of IL-17." (PMID 32260590, 2020). "TH17 cells produce the effector cytokines IL-17A, IL-17F, IL-22, and GM-CSF to mediate pathological inflammation responsible for many types of autoimmune diseases; targeting TH17 cells is thus a potential treatment for these diseases." (PMID 30451821, 2018). "This subtype is involved in the pathological process of tumors, host defence, infection, autoimmune diseases, and transplant rejection through the secretion of certain cytokines, such as interleukin (IL)-17A, IL-17F, IL-21, IL-22, and IL-6." (PMID 28796055, 2017). "IL-17A plays a more important role in autoimmune diseases than IL-17F, and is a cytokine with a strong pro-inflammatory action." (PMID 28912678, 2017). "17A and IL-17F have been verified to play an important role in inflammation, autoimmune diseases, and human organ transplantation rejection." (PMID 27034760, 2016). "IL-17A and IL-17F, produced mainly by Th17 cells, have been found to be involved in the pathogenesis of autoimmune diseases including diabetes and chronic inflammation, such as periodontitis." (PMID 26924897, 2016). "T helper 17 (Th17) cells play a central role in inflammatory and autoimmune diseases via the production of proinflammatory cytokines interleukin- (IL-) 17, IL-17F, and IL-22." (PMID 26792955, 2015). "Additionally, we discuss the action of the new therapeutic antibody, which targets IL-17A and IL-17F, and the consequences of blocking IL-17F with respect to the gut microbiome and autoimmune diseases." (PMID 41142785, 2025). "Additionally, Th17 cells (IL-17A, IL-17F, IL-21, and IL-22) are known to play an inflammatory role in mediating autoimmune diseases.." (PMID 38685091, 2024). "However, involvement of the other IL-17 family cytokines such as IL-17F in autoimmune diseases is still elusive." (PMID 28210632, 2017). "IL-17A and IL-17F are the most intensively studied due to their role in both protective immunity against Candida albicans and their capacity to promote inflammation in autoimmune diseases such as rheumatoid arthritis and psoriasis." (PMID 31557985, 2016). "Both IL-17A and IL-17F are reported to be involved in multiple human autoimmune diseases, but their functions and potency may vary." (PMID 26325187, 2015). "While this T cell lineage is beneficial for defense against certain extracellular bacterial and fungal infections, the secretion of IL-17A and IL-17F by Th17 cells may contribute to autoimmune disease pathogenesis by promoting the accumulation of neutrophils within tissues." (PMID 23505568, 2013). "Firstly, we detected IL-2, IL-4, IL-5, IL-13, IL-17A, IL-17F, IL-22, IFN-γ, and TNF-α in the plasma to exclude the influence of infection or autoimmune disorders, and the standard curves were verified." (PMID 38343544, 2024). "T helper 17 (Th17) cells, a novel subset of CD4+ T cells, are known to secrete IL-17A, IL-17F, IL-22, GM-CSF, and IFN-γ, which are involved in inflammation, autoimmune diseases, and graft-versus-host disease (GVHD)." (PMID 37063881, 2023). "Th17 cells, a key player in autoimmune diseases and antibiosis, are differentiated from naïve T cells (CD4+) stimulated by IL-6, TGF-β, IL-1β, IL-21 and IL-23 and release IL-17A, IL-17F, IL-21 and IL-22." (PMID 28899359, 2017). "Puel and colleagues detected high titer AAbs to one or more of IL-17A, IL-17F and/or IL-22 in 33 patients with APECED, but not in patients with other autoimmune disease or healthy controls, and demonstrated functional inhibition of IL-17A in vitro using plasma from one of these patients." (PMID 31557985, 2016).